BRCA1 (BRCA1 DNA repair associated)
Diseases named in the same sentence as BRCA1 in open-access papers (continued):
Sharing a sentence is not in itself a finding about the gene and the disease.
tumor (continued). "However, the underlying mechanism is likely more complex, and the delayed tumor formation could also be due to a non-HR DNA repair defect, a DNA replication defect or other defects that lead to cell death or senescence upon combined loss of BRCA1 and PALB2." (PMID 33893322, 2021). "The first, and most frequent, non-BRCA1/2 alteration seen was in BARD1, detected in four tumours." (PMID 34680387, 2021). "In this respect, it is worth noting that no one tumor had a deep (homozygous) co-deletion of both BECN1 and BRCA1, which is consistent with the fact that complete loss of these tumor suppressor genes is incompatible with cell survival." (PMID 33670664, 2021). "One of these tumours had a concomitant alteration in BARD1, and a second in BRCA1 and RMI1." (PMID 34680387, 2021). "RNA-seq data also showed that THZ1 could diminish transcripts of MYC-targeted genes, such as HK2, CDC25A, GLUT1 (SLC2A1), PD-L1 (CD274), BRCA1, and BRCA2, which are important mediators of MYC’s function in tumor metabolism, immune evasion, and DNA repair." (PMID 32690037, 2020). "In addition, the expression of two robust tumor suppressors PTEN and BRCA1 was upregulated after silencing circIQCH." (PMID 32756009, 2020). "Clustering of tumour and healthy lung samples in a 2D map using t-SNE algorithm based on the normalized expression levels of XIST, TSIX, hnRNPu, Bcl-2, and BRCA1, revealed that collectively these five genes -when assessed together- can have a diagnostic potential in both LUAD and LUSC." (PMID 33255394, 2020). "To confirm these findings, we analyzed peripheral blood DNA from 71 additional SCAN-B cases from our cohort not subjected to prior clinical screening, including 39 cases with tumor BRCA1 hypermethylation and 32 without." (PMID 32719340, 2020). "In conclusion, our results indicate that NOTCH1 may be an oncogenic driver for BRCA1-related TNBC and basal-type tumours." (PMID 32591500, 2020). "BRIP1, a DNA‐dependent ATPase and a 5'‐3' helicase that belongs to the DNA‐dependent RecQ DEAH helicase family, interacts with BRCA1 and is involved in double‐stranded DNA breaks (DSB) repair during the G2‐M phase of the cell cycle as well as in tumour suppression." (PMID 32888398, 2020). "The normal transactivation activity of BRCA1 is required to activate GADD45, as tumor-derived mutants of BRCA1 did not do so." (PMID 32013256, 2020). "3.3, we show the nodes having high role A and B motif centrality, such as HIFs, HDAC, BRCA1, EGR1, STAT1, GATA1 and GATA3, and also report their functions as master regulators in liver function, cell proliferation, tumor suppression and genomic stability, etc. as well as stress response." (PMID 32541819, 2020). "The overlapping peaks between BRCA1 and these factors were significantly reduced during the normal-to-tumor transition (p value < 2 × 10−16 for binomial tests in both cases)." (PMID 32615918, 2020). "In comparison, 84% of BRCA1 germline cases showed LOH of the wild-type allele, again with low associated tumor cell content for cases without LOH (n = 3, 11%, 18%, and 27% by WGS)." (PMID 32719340, 2020).
tumor (continued). "From these, we selected tumor samples with biallelic loss of BRCA1 or BRCA2, and non-mutated BRCA1/2, to obtain a high confidence set of samples belonging to three classes for classifier training (BRCA1-deficient, BRCA2-deficient, and BRCA1/2-proficient)." (PMID 33149131, 2020). "By logistic regression, stathmin protein independently predicted a BRCA1 genotype (OR 10.0, p = 0.015) among ER negative tumours." (PMID 32076022, 2020). "ERα+ BCs arising in BRCA1-mutated carriers typically show characteristics of biological and clinical aggressiveness, including a higher tumor grade and higher proliferation rates when compared with ERα+ BC occurring in BRCA1 non-carriers." (PMID 33316954, 2020). "While there are no recommendations about the timing of BRCA1/BRCA2 mutation analysis concerning pre- and post-therapeutic tumor samples, an adequate collection of tumor samples with a high tumor content prior to surgery is advised." (PMID 32850417, 2020). "So far, none of the many attempts of setting up IHC BRCA1 staining to assign the tumor BRCA1 status has been successful." (PMID 32290274, 2020). "We found that the treatment delayed tumor recurrence and blocked lung metastasis of the Brca1 mutant tumor (15.3%) compared to no treatment group (64.2%)." (PMID 32195105, 2020). "Three cell lines were chosen for our study: the MCF7 cell line from a luminal tumor, and the HCC1937 and MDA-MB-231 cell lines from basal-like tumors bearing or not (respectively) a mutation of the BRCA1 gene." (PMID 33162807, 2020). "FAM110B played a negative role in the translational regulation of BRCA1, which is a tumor suppressor of BRCA." (PMID 32984314, 2020). "Meanwhile, miR-182 inhibits BRCA1, a tumor suppressor involved in DNA repair, and MTSS1, a metastasis suppressor, and upregulates the EMT promoter HMGA2, thus increasing EOC cell invasiveness in vitro and tumor metastasis in vivo." (PMID 32993038, 2020). "As we know, the BRCA1 gene has great influence on HDR, which is critical for tumor suppression." (PMID 33408741, 2020). "Tumor samples were obtained from 30 patients with pathogenic germline variants in BRCA2 (n = 25) and BRCA1 (n = 5), as well as from an additional 30 patients without pathogenic germline mutations." (PMID 33067557, 2020). "Thus, co‐treatment of GC (HS746T and AGS, with higher and lower expression of BRCA1/2 and c‐MET, respectively) cell lines with PARP and c‐MET inhibitors reduces cell viability through apoptosis and attenuated tumour growth in xenograft models." (PMID 32686903, 2020). "BRCA1 and BRCA2 are tumour suppressor genes located on chromosomes 17 and 13 respectively." (PMID 32022473, 2020). "Among the clinically screened patients without a pathogenic germline BRCA1/BRCA2 variant, 16 out of 34 (47.1%) displayed tumor BRCA1 hypermethylation while 18 did not." (PMID 32719340, 2020). "BRCA1 expression analysis in TNBC tumors, sub-grouped on the basis of miR-9 expression, revealed that tumors with higher miR-9 expression in tumor or fibroblast compartment also over-expressed BRCA1, further supporting the correlation of high miR-9 expression to a chemo-resistance phenotype." (PMID 32972039, 2020). "The tumours of both groups also had a similar incidence of TNBC, i.e., 57% (85/149) and 50% (5/10), respectively, which is also comparable to the incidence of TNBC in human BRCA1-related breast cancers." (PMID 32591500, 2020).
tumor (continued). "In this study, we aimed to estimate the prevalence of germline and somatic BRCA1 and BRCA2 variants in a consecutive series of non-mucinous ovarian cancer patients and to evaluate the advantages and limitations of the tumor testing first strategy." (PMID 32850417, 2020). "Her tumor showed the similar BRCA1 5370C>T (R1751X) alteration but notably also showed a CCNE1 copy number of 7 by WES." (PMID 32709856, 2020). "Tumours sensitive to PARP inhibitors (PARPi) have a non-functional HR pathway due to aberrations in either BRCA1/2 or other components of the HR pathway." (PMID 34316683, 2020). "USP1 inhibitors have been proven effective in BRCA1 mutant tumours as USP1 is required for replication fork stability in the absence of functional BRCA1." (PMID 31769469, 2019). "We tested this hypothesis by studying the expression of total collagen, fibronectin, Ubc9, SIRT1, β-catenin in BRCA1 mutant TNBC cells and tumor sample derived from patient with dense breasts using immunofluorescence, immunohistochemistry, and collagen assay." (PMID 33860286, 2019). "sh-CTSS/sh-BRCA1 group showed less tumor delayed response than that of sh-CTSS alone xenografted group, suggesting antitumor effects by CTSS inhibition is occurred only in the presence of functional BRCA1." (PMID 30006610, 2019). "Currently, there is a lack of research on circRNAs that regulate the BRCA1 gene in tumor cells, including GC." (PMID 30927924, 2019). "Now, new roles for BRCA1 and BRCA2 are emerging and old concepts,such as the classical two-hit hypothesis for tumor suppression, have beenquestioned, at least for some BRCA functions." (PMID 31067289, 2019). "We defined 5 HGSC groups, representing BRCA1-mutant (clusters 1, 10; n = 36), BRCA2-mutant (cluster 4, n = 19), FBI (clusters 2, 5, 7; n = 50), Intra-Chr (cluster 8, n = 8), and CDK12-like tandem duplicator tumours (cluster 11, n = 5)." (PMID 30794536, 2019). "The depressed expression of BRCA1/2 and the increase of poly-ADP-ribosylation mediated by BKM120 could subsequently sensitize PARP inhibition in patient-derived primary tumor xenografts." (PMID 31295843, 2019). "Interestingly, Palb2-KPC tumors showed a mixture of Brca1-KPC and Brca2-KPC tumor phenotypes regarding the presence of cysts." (PMID 31877165, 2019). "As a transcriptional co‐repressor, there is still no direct evidence to support the notion that BRCA1 mediates tumor metabolic adaptation through its transcriptional function." (PMID 30714292, 2019). "Allele XRCC3-241Met (OR 0.85, 95%CI 0.72–0.99, p < 0.045), XRCC2-41657 T (OR 1.67, 95% CI 1.42–1.96, p < .0001), BRCA1-356R (OR 1.61; % CI 1.37–1.90, p < .0001) and RAD51–135C (OR 5.16; 95% CI 4.29–6.20, p < .0001) strongly correlated with the neoplastic disease." (PMID 30712190, 2019). "A meta-analysis showed that women with BRCAm (not specified if somatic mutation carriers are included) OC have an increased OS (BRCA1: HR 0.76, 95% CI: 0.70–0.83; BRCA2: HR: 0.58, 95% CI: 0.50–0.66), regardless of tumour stage, grade, or histologic subtype." (PMID 30909618, 2019). "Contrasting this are results from the recently published TnT trial, where patients with triple negative metastatic breast cancer and tumor BRCA1 methylation did not respond any better to platinum chemotherapy than those without such epimutations." (PMID 31225507, 2019). "BRCA1, BRCA2 and NBN act as classical tumor suppressor genes." (PMID 31614901, 2019). "Some pathogenic mutations were detected in the patients’ familiy members without the past history of tumor and 92 novel mutations were detected (31 on BRCA including 2 P, 16 LP, 13 VUS; 61 on non‐BRCA1/2 including 9 LP, 52 VUS)." (PMID 30982232, 2019).
tumor (continued). "Furthermore, PS cells overexpressed BRCA1 and SPARCL1, already known in GBM to promote tumor cell viability, migration and invasion and to correlate with patients prognosis." (PMID 31231613, 2019). "We have shown that wild type BRCA1 proteins, unlike the disease-associated mutant BRCA1 proteins, bind the sole SUMO E2-conjugating enzyme Ubc9 and function as a tumor suppressor." (PMID 33860286, 2019). "The rate of BRCA1/BRCA2 mutation detection in those studies, selected based on the tumor triple negativity, independent of family history, varies from 17.4% to 49.1%." (PMID 31244284, 2019). "A recent study showed that SOX2 overexpression was found in a proportion of women with BRCA1 and BRCA2 mutations who underwent prophylactic salpingo-oophorectomy, and in the majority of patients with HGSOCs, irrespective of tumor stage." (PMID 31850198, 2019). "Secondary BRCA1/2 mutations and NER-related alterations also were searched in nonpaired fresh tumor samples and in all archival tumor samples available (n = 7 primary; n = 5 metastatic)." (PMID 30240327, 2018). "For example, using point mutations that separately disrupt the RING and BRCT domains, it was shown that some functions of the latter (BRCT phospho-recognition) but not the former (E3 ligase activity) are essential for BRCA1-mediated tumor suppression." (PMID 29426838, 2018). "We showed that estrogen does not activate EMT in ER-positive and Brca1-proficient tumor cells in vitro and tumorigenesis in vivo." (PMID 29996906, 2018). "Platinum agents have been shown to be more effective in tumours with deficient DDR, potentially due to their ability to cause DNA strand crosslinking and induce double-strand breaks, which together with BRCA1/2 mutations, will not be effectively repaired." (PMID 29329208, 2018). "As dysfunction of BRCA1 and BRCA2 promotes carcinogenesis through promoting genomic instability 16, PALB2 has been hypothesized to be a tumor suppressor gene." (PMID 29321957, 2018). "Olaparib as a single agent is widely used in BRCA1 or BRCA2 mutant tumor cells, but had less effect in CCA cells without BRCA1 or BRCA2 mutations, with a half maximal inhibitory concentration (IC50) close to 10 μmol/L." (PMID 29479816, 2018). "In breast cancer, the most used prognostic factors include patient characteristics (age and menstrual status), tumor features (tumor size, node status, and TNM stage), tumor tissue markers (estrogen receptor, progesterone receptor, HER-2 status, and ki-67 status), and genetic markers (BRCA1/2)." (PMID 29854028, 2018). "Tumor cells defective in BRCA1/2 may rely on PAPR-dependent DNA repair, and therefore are sensitive to PARP inhibitors, which may also increase the sensitivity of tumor cells to DNA-damaging agents." (PMID 30333000, 2018).
tumor (continued). "Analysis of a tumor sample collected from a patient with BRCA–wild-type/LOH-low genotype who had a complete response to rucaparib showed amplification of cyclin E1 (CCNE1), which is able to suppress BRCA1 expression." (PMID 30518089, 2018). "Conversely, no disease stabilization or tumor regression was observed in response to rucaparib for either PDX #48 or #169 both of which harbored heterozygous BRCA1 promoter methylation." (PMID 30266954, 2018). "In addition, reversion mutations leading to regained function of HR-proteins (e.g., BRCA1, RAD51C and RAD51D) in tumor cells result in PARP resistance." (PMID 30441849, 2018). "The absence of histological resemblance between BRCA1- and ATM-associated tumours was reflected at the molecular level." (PMID 29665859, 2018). "Except for few being chromatin regulators (CGBP, MBD2, and DNMT1), all of these TFs were found to have tumor suppressor functionality (BRCA1, E2F1&2&5&7, EGR1-4, FLI1, NRF1, TFDP2, and STAT1), or indirectly mediate the suppression of tumorigenesis and tumor suppressor activity (SP4 and ZBTB33)." (PMID 29740534, 2018). "In contrast, all BRCA1-mutated tumors with locus-specific LOH had decreased or absent BRCA1 nuclear staining compared to normal stromal cell nuclei within the tumor." (PMID 28831036, 2017). "For example, unlike humans, tumour incidence is not higher in heterozygous Brca1 KO mice versus WT mice." (PMID 28649985, 2017). "Statistically significant difference between TNBCs and non-TNBCs and tumor stage with regard to BRCA1-IRIS-overexpression was observed." (PMID 28499366, 2017). "Based on the genetic heterogeneity of the observed mutation spectrum, sequencing of the entire open‐reading frame (ORF) of BRCA1 and BRCA2 using tumor‐derived DNA is required to identify the patients who may benefit from this treatment." (PMID 27767231, 2017). "In addition, we found under-representation of methylated nucleotides in BC cell lines derived from tumours that were classified as TNBC, in addition to altered BRCA1 functionality." (PMID 29259228, 2017). "If both copies of either BRCA1 or BRCA2 are mutated, HR fails to be initiated, resulting in genomic instability and consequently tumour initiation." (PMID 29021870, 2017). "This datum is noteworthy, since low-intermediate grade tumours are not frequently found in BRCA1/2 families and are considered to be negative predictors of the BRCA mutation status." (PMID 28199346, 2017). "For the following genes, a correlation was found between the methylation levels in tumors and those in tumor-adjacent tissues: CDKN2A (promoter) (r = 0.927, p < 0.001); BRCA1 (r = 0.878, p < 0.001); APC (r = 0.706, p = 0.001), ESR1 (r = 0.545, p = 0.019) and ESR2 (r = 0.543, p = 0.024)." (PMID 28403857, 2017). "However, in response to IR, some tumor cells activate DSBs repair and pro-survival pathways such as EGFR/ATM/ATR/BRCA1/Chk1 and PI3K/Akt or RAS/Raf/ERK1/2, rendering them radio-resistant." (PMID 28423495, 2017). "There was a trend towards having high grade tumor, negative hormone receptors, low bcl2 expression and high Ki67 index in cases with low nuclear BRCA1 expression." (PMID 28863181, 2017). "Despite the discrepancy, it should be noted that our results do not contradict the argument that the E3 ligase activity of BRCA1 is dispensable for tumor suppression." (PMID 28398198, 2017). "Thus, functional antagonism between BRCA1 and NELF enforces a fine balance between normal tissue development and tumour suppression." (PMID 28649985, 2017).